IL4 (interleukin 4)
Diseases named in the same sentence as IL4 in open-access papers (continued):
Sharing a sentence is not in itself a finding about the gene and the disease.
malaria (continued). "As with the subgroup analysis of types of severe complications, the meta-analysis of studies that enrolled patients with cerebral and noncerebral severe malaria revealed a trend toward lower IL-4 levels in patients with severe malaria compared to patients with uncomplicated malaria." (PMID 35820892, 2022). "Vaccines against blood-stage malaria often aim to induce antibodies to neutralize parasite entry into red blood cells, interferon gamma (IFNγ) produced by T helper 1 (Th1) CD4+ T cells or interleukin 4 (IL-4) produced by T helper 2 (Th2) cells to provide B cell help." (PMID 33153189, 2020). "Whilst interleukin 4 (IL4) production by T helper 2 (Th2) T cells can support antibody production by B cells, IFNγ production by γδ T cells and T helper 1 (Th1) CD4+ T cells has been suggested to also play a role in mediating blood-stage protection in rodent malaria models." (PMID 33153189, 2020). "Severe malaria was also associated with higher levels of IL-1β (p = 0.008), IL-2 (p = 0.001), IL-4 (p = 0.041), IL-12p70 (p = 0.010), IL-13 (p = 0.004), IFN-γ (p = 0.041), TNF (p = 0.049), IFN-γ/IL-10 (p = 0.016), TNF/IL-10 (p = 0.016) and (TNF + IFN-γ)/IL-10 (p = 0.001) than mild malaria." (PMID 26466783, 2015). "IL-4 production was virtually absent in T cells from malaria-infected C57BL/6 mice (not shown)." (PMID 19343215, 2009). "In our study, IL-4 and IL-10 concentrations were higher in patients with severe malaria than in patients with non-severe malaria, consistent with that reported by other authors; the increase in these cytokines may reflect the immune response controlling the infectious process." (PMID 36178979, 2022). "Additionally, the subsets of CD4+ T cells that secrete IL-4 or IL-12 provide help in inducing the CD8+ T cell responses and for optimal CD8+ T cell effector activities, respectively, suggesting a CD4–CD8 cross-talk for the development of anti-malaria protective immunity." (PMID 34376691, 2021). "Although P. vivax and P. falciparum malaria patients have similar cytokine profiles during infection, in P. vivax acute phase malaria, APRIL but not BAFF levels correlated positively with IL‐1, IL‐2, IL‐4, IL‐6, and IL‐13 levels." (PMID 29314720, 2018). "It was found that HB and HT displayed several negative significant interactions mainly with IL-4, IL-5, IL-12p70, and IL-17, whereas ALT interacted negatively with IL-4 and IL-7 in the malaria group." (PMID 26271921, 2015). "In the context of laboratory and immune markers correlations, the group of individuals presenting with malaria mono-infection displayed significant negative correlations between ALT and IL-4 and IL-7." (PMID 26271921, 2015). "The assayed cytokines were detectable in the placental sera (IFN-γ, IL-12, IL-4, IL-6 and IL-10) and plasma (TNF-α) samples extracted from malaria-infected and malaria-negative olive baboons." (PMID 26623293, 2012). "Malaria infection in the collected maternal peripheral, placental, umbilical cord samples was determined microscopically, and ELISA was used to measure the plasma levels IL-4, IL-6, IL-10, IL-17A, and INF γ in the collected positive and negative malaria samples." (PMID 33422078, 2021). "Indeed, our findings showed that, in P. vivax acute phase malaria, APRIL but not BAFF levels correlated positively with IL‐1, IL‐2, IL‐4, IL‐6, and IL‐13 levels." (PMID 29314720, 2018).
periodontitis (102 papers, 2007 to 2026). An acute or chronic inflammatory process that affects the tissues that surround and support the teeth. "Oral administration of Cur can relieve bone absorption caused by periodontitis and reduce the expression of interleukin-4 (IL-4) and tumor necrosis factor-α (TNF-α) in the gingiva." (PMID 38549147, 2024). "In 104 patients with periodontitis, IL4 haplotypes were significantly associated with levels of A. actinomycetemcomitans before and after periodontal treatment." (PMID 35122548, 2022). "IL-4 −590 C/T T allele had a weak relationship with the periodontitis risk with OR (95% CI), 0.92 (0.72–1.11)." (PMID 35046930, 2021). "Previous studies have investigated the pathogenesis of periodontitis and its association with the inflammatory cytokines IL-1β, IL-4, IL-6, IL-10, interferon-γ (IFN-γ), and TNF-α39." (PMID 34764408, 2021). "The IBD activity was associated with significantly increased expression of IL-4, IL-10 and IL-21 in the gingival tissue of patients with periodontitis." (PMID 34501547, 2021). "Currently, studies investigating the association between IL-4 gene polymorphisms and periodontitis mainly focus on its promoter region." (PMID 28392616, 2017). "In conclusion, IL-4 genetic variations associated with susceptibility to or protection against chronic periodontitis are directly associated with influencing the response of immune cells to periodontopathogens." (PMID 28114408, 2017). "In the present study, we systematically searched and evaluated case-control studies addressing the association between IL-4 and IL-4R polymorphisms and periodontitis susceptibility." (PMID 28392616, 2017). "The association between gene polymorphisms in chronic periodontitis and response to treatment was examined in patients that presented a susceptible genotype in the following genes IL-1, IL-4, IL-8, MMP-13, MMP-1 and MBL." (PMID 26595831, 2016). "The haplotype T(-590)/T(-33)/allele 2 VNTR (70 base pairs) of the IL-4 gene was significantly more frequent in patients with chronic periodontitis." (PMID 26595831, 2016). "The levels of regulatory cytokine IL-10 in patients with periodontitis carrying the appropriate genotypes of IL-4 polymorphisms were also significantly increased, after stimulation with P. intermedia." (PMID 25530681, 2014). "Production of IL-1β was significantly higher in patients with periodontitis carrying the CC genotype IL-4 -590C/T variant after stimulation with T. forsythia and in the unstimulated culture (P < 0.05)." (PMID 25530681, 2014). "The aim of this study was to evaluate the occurrence of IL-4 gene polymorphisms in chronic periodontitis and to investigate the association between polymorphisms and cytokines production after bacterial stimulation." (PMID 25530681, 2014). "Based on our previous results, we assumed that, after stimulation with dental plaque bacteria, IL-4 gene polymorphisms in periodontitis patients would in particular affect the production of cytokine IL-4." (PMID 25530681, 2014). "In contrast, our results demonstrated an association of IL-4 C/C genotype (OR = 16.003; 95% CI = 2.178 - 117.563) with a lower frequency in periodontitis patients." (PMID 23046796, 2012). "The odds ratio for carriage of IL-4 allele (T/T and C/T genotypes combined compared with the C/C genotype) was 16.003 (95% CI = 2.178 - 117.563) in periodontitis patients." (PMID 23046796, 2012). "In addition, the IL‐1β/IL‐10 ratio and TNF‐α/IL‐4 ratio in the biopsies of periodontitis patients are strongly associated with the severity of periodontitis." (PMID 37647428, 2023). "The IL-4 −33 CT genotype was negatively associated with the occurrence of aggressive periodontitis." (PMID 35454140, 2022). "However, in the Japanese population, a more common combination of −590 (C → T) polymorphism in the IL-4 promoter with intron 2 polymorphism in healthy subjects than in patients with aggressive periodontitis was observed." (PMID 35454140, 2022).
periodontitis (continued). "Among these inflammatory factors, Interleukin-4 (IL-4), a cytokine involved in the process of inflammation, is closely associated with the pathogenesis of periodontitis through enhancing Th2 cell proliferation, suppressing Th1 cell proliferation, and downregulating Th1-mediated immune response." (PMID 28392616, 2017). "In the present study, we performed meta-analyses concerning the relationship between susceptibility and periodontitis (including CP and AgP) and polymorphisms including the IL-4 -590C/T, -33C/T, -1099T/G, 70-bp VNTR, and IL-4R Q551R, in the overall population and specific subgroups." (PMID 28392616, 2017). "In addition, polymorphisms in the IL-4 promoter and intron that are associated with decreased serum levels of IL-4 are also associated with increased susceptibility to early onset periodontitis." (PMID 17319946, 2007). "Additionally, chronic periodontitis is associated with elevated systemic levels of other pro-inflammatory mediators, such as fibrinogen, haptoglobin, and IL-18, alongside decreased anti-inflammatory markers like IL-4." (PMID 40136726, 2025). "In the second protocol, the mice with Periodontitis showed decreased cardiac output (10 ± 0.8 vs. 15 ± 1.4 mL/min in Sham) and ejection fraction (37 ± 3 vs. 47 ± 2% in Sham) associated with increased myocardial cytokines (Interleukin-17, Interleukin-6, and Interleukin-4)." (PMID 32327711, 2020). "Besides, increased salivary IL-4 also has been associated with periodontitis." (PMID 31973090, 2020). "In addition, two more polymorphisms, that is, the IL-4-1099T/G and IL-4R Q551R, are discussed in our study, and it is revealed that the IL-4R Q551R allele may increase the susceptibility to periodontitis in Caucasians." (PMID 28392616, 2017). "Some studies suggest an association between genetic polymorphisms of IL-1 and IL-4 coding genes and MMP-1 gene promoter and periodontitis in CKD patients." (PMID 39652270, 2025). "Supplementation with α-KG can reverse the inhibitory effects ofP. gingivalis and IL-4 on the polarization of M2 macrophages and alleviate periodontitis." (PMID 39967425, 2025). "The results provided genetic evidence for significant associations between genetically predicted levels of family Pasteurellaceae, 45 blood metabolites, and 4 inflammatory proteins (IL-4, IL-22RA1, S100-A12, TNFSF12) and periodontitis susceptibility." (PMID 41001956, 2025). "On the one hand, LPS and IL-4 expressed byPorphyromonas gingivalis can promote the polarization of M1 macrophages and inhibit the polarization of M2 macrophages, exacerbating periodontitis." (PMID 39967425, 2025). "Common inflammation biomarkers in saliva and plasma in patients with DM2 and periodontitis; p1 = 0.003 (IL-10) and p2 < 0.001 (IL-4)." (PMID 38727455, 2024). "The health of the periodontal tissues is closely related to interleukin 4, which has an important and central role in the pathogenesis of periodontitis, this being demonstrated in numerous studies in the specialized literature." (PMID 38920850, 2024). "We highlight that curcumin significantly increases IL-4 concentrations 42 and insignificantly IL-10 levels 53 in subjects with periodontitis." (PMID 39912085, 2024). "In comparison to healthy gingival samples, patients with chronic periodontitis had significantly lower levels of IL-4 and IFN." (PMID 38420070, 2024). "Compared to healthy gingival samples, patients with chronic periodontitis had significantly lower levels of IL4 and IFN." (PMID 38420070, 2024). "We evaluated the effects of ω-3 PUFA on the cytokines TNFα, IL-2, IFNγ, IL-4, and IL-5 in a P. gingivalis ligature-induced periodontitis in the serum of mice." (PMID 37378834, 2024). "One case–control study demonstrated higher GCF levels of IFN-γ and lower levels of IL-4 in patients with recurrent miscarriage and periodontitis in comparison to patients with uncomplicated pregnancies." (PMID 37342498, 2023).
periodontitis (continued). "It should be pointed out that periodontitis fosters a proinflammatory microenvironment, and the levels of IL-1β, IL-4, IL-10, and IL-17A were significantly higher in diseased sites than healthy sites in the same oral cavity from periodontitis patients." (PMID 36949458, 2023). "IL-4 and IL-10 in the periodontitis groups were significantly lower than the healthy group (p < 0.0001) and barely improved following SRP up to the level of the healthy group." (PMID 37246231, 2023). "GCF levels of IL-4 were decreased in patients with recurrent miscarriage and periodontitis as compared to women with uncomplicated pregnancies." (PMID 37342498, 2023). "Some authors have described absence or very low levels of IL-4 in both healthy individuals and periodontitis patients, whereas others report lower levels in gingival samples of periodontitis subjects." (PMID 37246231, 2023). "A previous meta-analysis has indicated consistent down-regulation of IL-4 in patients with chronic periodontitis and elevation of its levels following treatment of this condition." (PMID 36456933, 2022). "The results showed a decreased IL4 expression in periodontitis subjects in comparison with controls (17.8 ± 3.6 vs. 41.5 ± 2.1; p = 0.05)." (PMID 36233348, 2022). "Taking together, the higher levels of aMMP-8 and PGE2 identified with the coexistence of IBD and periodontitis and lower levels of IL-4 seems to alter immunological traits in GCF negatively." (PMID 34501547, 2021). "Regarding the local impact of periodontitis, previous research has shown that decreased levels of IL-4 and increased levels of MMP-8, PGE2 and S100A12 in the oral cavity are associated with higher periodontal deterioration." (PMID 34501547, 2021). "In this way, when periodontitis becomes chronic, negative regulation of inflammation through the anti-inflammatory cytokines IL-4, IL-6, IL-10, IL-11, and IL-13 becomes predominant." (PMID 34707462, 2021). "The concentration of IL-6, IL-4 and IL-17 in the heart was assessed to examine the inflammatory response elicited by periodontitis." (PMID 32327711, 2020). "IL-4 suppress the production of IL-17 and IL-1β, which play an important role in the periodontitis pathogenesis and inhibit both Th1 pro-inflammatory response and bone resorption." (PMID 31035477, 2019). "In contrast, the lower levels of IL‐4 and Th2 in the CP group demonstrated that when the Th1/Th2 balance is disturbed in periodontitis patients, the proinflammatory Th1 cell role was promoted, whereas the anti‐inflammatory Th2 cell role was inhibited." (PMID 31944625, 2019). "On the one hand, IL-4 was determined by meta-analysis to be the only cytokine decreased in chronic periodontitis patients and elevated after periodontal treatment, which indicates that IL-4 and Th2 cells have protective effects in periodontitis." (PMID 31685798, 2019). "In the present study, other ratios such as IL17A/IFNgamma, IL17A/IL2, IL17A/IL3 and IL17A/IL4 had significantly higher values in the periodontal patients, reflecting their impact on chronic periodontitis." (PMID 30573746, 2018). "RA patients with periodontitis on DMARDs have been found to exhibit lower local IL-1β, IL-4, and TNF-α levels than otherwise healthy patients with periodontitis, however, the study about the effect of DMARDs on clinical periodontal parameters is limited." (PMID 30211216, 2018). "Curiously, however, our results were contrary to those reported by these authors, as four anti-inflammatory cytokines (IFNgamma, IL2, IL3 and IL4) showed significantly higher concentrations in chronic periodontitis than in health." (PMID 28912468, 2017). "Polymorphism in the IL-4 gene has been investigated and it has been reported that individuals-carriers of the TCI/CCI haplotype are more susceptible to chronic periodontitis than those who carry the TTD/CTI haplotype." (PMID 26595831, 2016).
periodontitis (continued). "A modest study of 20 periodontitis patients and 20 controls demonstrated that IL-4 decreased significantly and sTLR2 increased significantly following such treatment." (PMID 24944840, 2014). "In our study, however, the IFNγ/IL4 imbalance was also observed in response to TT, an Ag irrelevant to periodontitis." (PMID 23335969, 2013). "The presence of IL-4-producing cells and the percentage of IL-4-expressing cells were significantly higher in established and severe periodontitis lesions than in gingivitis tissues." (PMID 23046796, 2012). "The aim of this study is to compare genotypes and soluble protein of pro and anti-inflammatory cytokines (IL-1α, IL-1β, IL-6, IFN-γ, IL-10, TNF-α and IL-4) in subjects with or free of chronic periodontitis." (PMID 23046796, 2012). "While some studies suggest a possible destructive role for IL-4 in both chronic and aggressive periodontitis, other studies suggest that this cytokine has a protective role against tissue destruction." (PMID 20383335, 2010). "Out of the most studied genes in aggressive periodontitis [IL1-A and IL1-B (2q14), IL-4 (5q31.1), IL-10 (1q31-q32), FcγRIIa, FcγRIIb, and FcγRIIIb (1q23), and TNFA (6p21.3)], IL-4 and TNFA map in the intervals with suggestive association results." (PMID 20383335, 2010). "In the paper that compared cytokine levels for 54 periodontitis patients and 40 healthy controls, cytokines IL‐1β, IL‐4, IL‐6, IL‐10, IL‐17A, IL‐17F, IL‐21, IL‐22, IL‐23, IL‐25, IL‐31, IL‐33, IFN‐γ, sCD40L and TNF‐α were measured in saliva and serum at baseline, 3, 6 and 12 months after treatment." (PMID 41580300, 2026). "CD8 + T cell clones, which can originate from periodontitis-affected tissues, may secrete cytokines like IL-4 and IL-5 to inhibit the production of IFN-γ and promote humoral immune responses." (PMID 39014403, 2024). "The presence of inflammatory mediators in periodontitis, such as IL-1, IL-1 β, IL-4, IL-6, IL-8, IL-10, TNF and IFN-γ, together with macrophages sensitized by M. leprae in the bloodstream can exacerbate the host’s immune response, triggering the leprosy reaction." (PMID 37418096, 2023). "We also observed that six molecules (IL-4, IL-5, IL-12, IL-13, IL-21, and IL-23) were intimately related in the periodontitis sites of all evaluated groups, regardless of risk factors." (PMID 37835794, 2023). "Interestingly, resveratrol also reversed the diabetic periodontitis-downregulated expression of anti-inflammatory factors IL-4 and IL-10 in osteocytes." (PMID 37432277, 2023). "Although many case-control studies have been conducted on the association of IL-4 with periodontitis, there is no longitudinal study that can be compared with the present analysis." (PMID 35806269, 2022). "The polymorphisms for the members IL-4 and IL-13 of Th2 cytokine family are not found to be associated with the pathogenesis of periodontitis." (PMID 35046930, 2021). "For example, a group of researchers has identified the association between the genetic risk factors of biomarkers (IL-1, IL-1β, IL-1α, IL-4, IL-10) and periodontitis in different populations, whereas others found no connection." (PMID 34684209, 2021). "While less IL-4 (linked to Th cell polarization toward the Th2 cells), IL-10 (linked to Th cell polarization toward the Treg) and transforming growth factor-β (TGF-β) are detected in the patients with periodontitis." (PMID 34868054, 2021). "The results are inconsistent with the previous report that IL-4 has been found to be decreased in chronic periodontitis subjects and increased after therapy, which implies that IL-4 in Th2 cells may have protective effects in the prevention of periodontitis." (PMID 35046930, 2021). "Surprisingly, in an animal model of both periodontitis and asthma, researchers reported that periodontitis in asthmatic mice resulted in reduced migration of eosinophils, lymphocytes, and macrophages into the airways, reduced levels of IL-4 and TNF-α, and decreased mucus production." (PMID 34765263, 2021).